SFT2D3 (SFT2 domain containing 3)
Description:
May be involved in fusion of retrograde transport vesicles derived from an endocytic compartment with the Golgi complex.
Synonyms: MGC5391
Tractability: Antibody: UniProt predicts a signal peptide or a membrane-spanning region. PROTAC: ubiquitination databases record sites on it; its protein half-life has been measured.
Gene: Protein-coding gene on chromosome 2 (127,701,497 to 127,705,242, forward strand). Ensembl gene ENSG00000173349.
Subcellular location: Membrane
Gene Ontology:
Biological process: vesicle-mediated transport
Cellular component: cytoplasm; endomembrane system; membrane
Genetic constraint (gnomAD): Loss-of-function variants: 0 observed, 0.0749 expected, observed/expected ratio (o/e) 0, 90% interval 0 to 1.89. That is too few expected variants to judge how well the gene tolerates losing a copy. Missense variants: 405 observed, 188.45 expected, observed/expected ratio (o/e) 2.15. Synonymous variants: 239 observed, 116.25 expected, observed/expected ratio (o/e) 2.06.
Homologues: Orthologues: chimpanzee SFT2D3 (99% identical), dog SFT2D3 (83% identical), pig SFT2D3 (81% identical), rat Sft2d3 (80% identical), mouse Sft2d3 (78% identical), tropical clawed frog sft2d3 (47% identical), zebrafish sft2d3 (44% identical), Caenorhabditis elegans sftd-3 (26% identical). Paralogues in human: SFT2D1 (20% identical), SFT2D2 (17% identical).